AURKA (aurora kinase A)
Diseases named in the same sentence as AURKA in open-access papers (continued):
Sharing a sentence is not in itself a finding about the gene and the disease.
cancer (continued). "Indeed, it has also been observed that overexpression of AURKA in breast, colorectal, and other cancers is associated with the amplification of the corresponding chromosomal region 20q13.2." (PMID 24876664, 2014). "AURKA overexpression is significantly associated with neoplastic transformation in several tumors and deregulated Aurora Kinases expression leads to chromosome instability, thus contributing to cancer progression." (PMID 21718475, 2011). "Overexpression of AurkA is associated with cancer, including human DCIS." (PMID 17147824, 2006). "Thus, upregulation of such oncogenic targets could be the primary event causing AURKA upregulation in these cancers, which in turn engages in a feedback loop with its targets." (PMID 39334449, 2024). "Additionally, AURKA polymorphisms have been correlated with an increased risk of cancer." (PMID 39834933, 2024). "Furthermore, exploiting AurkA synthetic lethal interactions with oncosuppressors frequently mutated in cancer may be a route with which to improve AurkA-based therapeutic strategies." (PMID 39195284, 2024). "However, the relationship between EGFR mutations and Gefitinib target genes (FBP1, SBK1, and AURKA) warrants further investigation, and cancer tissues were collected to confirm the relationship between the risk model and nomogram and the prognosis of LUAD patients in the future." (PMID 37737707, 2023). "In NSCLC, overexpression of AURKA was regarded as a poor prognosis and therefore AURKA inhibitors could not only cause G2/M arrest of cancer cells but also lead to the significant autophagy and enhance the anticancer activity of clinical medicine (Katayama and sen., 2010)." (PMID 36072340, 2022). "Stathmin‐mediated disruption of microtubule dynamics is a key factor that induces the combined lethality of RB1‐deficient cancers and suggests that upstream factors that regulate microtubule dynamics, such as AURKA could be potential therapeutic targets for RB1‐deficient cancers." (PMID 34799997, 2022). "Moreover, AURKA inhibition has synthetic lethality in cancer cells possessing RB1 mutation." (PMID 34359608, 2021). "Aberrant expression of AURKA may lead to genetic instability and cause development of many cancers." (PMID 31269749, 2019). "Whereas clonal evolution might allow certain cancers to evade immune surveillance by downregulation of antigenic genes (for example so-called ‘passenger mutations’), similar downregulation of AURKA expression in cancerous cells seems unlikely given its role as a driver of cancer progression." (PMID 27271876, 2016). "Furthermore, AURKA has been implicated as an oncogenic driver in human cancers." (PMID 26380223, 2015). "At the protein level, AURKA was significantly higher in both cancer groups compared to the control group (p < 0.001)." (PMID 41515655, 2026). "A comprehensive analysis of AURKA expression was performed in 33 cancer types, comparing normal and tumor samples from the TCGA dataset." (PMID 40718709, 2025). "AURKA is also regarded as an oncogene and is overexpressed in various types of cancers, contributing to tumor development." (PMID 39928563, 2025). "Based on the TCGA database, the expression of AURKA was significantly higher in cancer samples than in normal control samples." (PMID 40324248, 2025). "Because of a higher expression of genes related to cell proliferation and the cell cycle, such as Ki-67 and Aurora kinase A, luminal B cancers are therefore more aggressive than luminal A (low proliferative) cancers." (PMID 40176859, 2025). "AURKA has been garnering increasing recognition as a viable target for cancer therapy given its elevated expression across various malignancies." (PMID 39789853, 2025).
cancer (continued). "AURKA, a kinase with roles in mitosis and cancer cell survival, contributed most significantly to RB1 tumour classification." (PMID 40775769, 2025). "Overexpression or gene amplification of AURKA has been widely reported across various human cancers." (PMID 40949156, 2025). "In this study, we integrated TCGA pan-cancer multi-omics data and GEO data to analyze the RNA, methylation, protein expression, and genomic alteration characteristics of AURKA." (PMID 40718709, 2025). "The pan-cancer analysis demonstrated that AURKA expression heterogeneity was present among urological tumors at different molecular levels, and the positive correlation of AURKA alteration with MYC and E2F pathways was conserved in pan-cancer." (PMID 40718709, 2025). "The expression of 74 genes can influence the activity of multiple cancer hallmark-related pathways, such as MELK, CDC25C, and AURKA." (PMID 39940833, 2025). "In the correlation analysis with hallmark pathways, the AURKA expression had a strong and positive correlation with pathways such as MYC targets, G2M checkpoint, and E2F targets in the majority of cancers (correlation coefficients > 0.6)." (PMID 40718709, 2025). "Pandey utilized MolProphet platform to generate novel small molecules targeting aurora kinase A (AURKA) which is overexpressed in diverse types of cancer and acts as a synthetic lethal partner of several tumor suppressor genes." (PMID 41402855, 2025). "AURKA is one of the major regulators of the cell cycle, and an oncogene involved in tumorigenesis in several types of cancers that promotes centrosome amplification and tumor growth." (PMID 40057470, 2025). "We reported that ZNF468 counteracts radiation‐induced G2/M checkpoint arrest and cell death in ESCC by enhancing AURKA gene expression, thereby unveiling a pivotal mechanism by which cancer cells evade the cytotoxic effects of radiotherapy." (PMID 40702875, 2025). "When TIALD is stabilised, it suppresses cancer progression by promoting the degradation of Aurora kinase A (AURKA) through the lysosomal pathway, which inhibits tumour cell migration and invasion." (PMID 40944360, 2025). "Analysis of the TCGA-Pan-Cancer dataset revealed elevated AURKA expression across multiple tumor types relative to normal tissues." (PMID 41471272, 2025). "Examining the expression level of AURKA in different cancers indicates that this gene can act as an oncogene or a tumor suppressor gene." (PMID 40723362, 2025). "Recent studies indicate that downstream genes of the DREAM complex, such as FOXM1, PLK1, and AURKA, are critical for cancer cell proliferation across various cancers." (PMID 39796178, 2025). "As an oncogene, AURKA overexpressed in a variety of tumors and plays multiple roles in cancer development." (PMID 40311679, 2025). "Subsequent pan-cancer analysis revealed correlations between AURKA expression patterns and 28 immune cell subtypes across 33 malignancies." (PMID 41357242, 2025). "AURKA promotes cancer cell survival, and consistent with our model’s finding, its inhibition has been shown to be effective in RB1 mutant cells." (PMID 40775769, 2025). "BRCA2-deficient cancer exhibits heightened sensitivity to TPX2 and AurkA inactivation through alisertib treatment, which delays mitotic progression." (PMID 40362354, 2025). "AURKA overexpression has been found to correlate with metastasis and poor prognosis in several cancers, suggesting that it is a promising target for treatment and a prognostic biomarker." (PMID 40718709, 2025). "AURKA (Aurora kinase A) is a serine/threonine kinase critical for mitosis and cellular proliferation, frequently dysregulated in cancers and contributing to their progression." (PMID 41024254, 2025). "Alisertib is a selective, potent, and reversible small‐molecule inhibitor of AURKA that has been studied in several cancers." (PMID 39789853, 2025).
cancer (continued). "The mitotic kinase AURKA has gained much attention as a potential therapeutic target against cancer because of its essential role in the cell cycle." (PMID 40107714, 2025). "The research revealed significant variations in the different molecular levels of AURKA expression across pan-cancer, such as at the RNA, methylation, and protein levels." (PMID 40718709, 2025). "Compound 19 effectively reduced AURKA phosphorylation at Thr288, induced G2/M phase arrest, triggered apoptosis, and suppressed cancer cell migration and proliferation." (PMID 40949156, 2025). "A correlation analysis between AURKA and cancer stemness at the RNA level revealed a coefficient of 0.7 for UCEC and BRCA." (PMID 40718709, 2025). "Most cancer samples showed an extensive range of data distribution, indicating variable levels of AURKA mRNA expression among cancer patients." (PMID 39527514, 2024). "Gene amplification and overexpression of AURKA have been detected in many cancers, including lung, ovarian, pancreatic, breast, and bladder cancer." (PMID 39199578, 2024). "The public web server GEPIA2 was consulted to retrieve information on the distribution of AURKA transcripts across TCGA cancers." (PMID 39527514, 2024). "Several studies have determined the expression profile of AURKA and its prognostic significance in a wide range of cancers using whole-genome datasets from TCGA, although limited by two main caveats." (PMID 39527514, 2024). "The median AURKA mRNA expression across normal tissues was tissue-dependent, and the overall AURKA mRNA levels in cancer also varied across tissues suggesting tissue-specific dysregulation." (PMID 39527514, 2024). "Early studies indicated that AurkA overexpression yields the overriding of the SAC in U2OS cancer cells treated with nocodazole, an effect that can become therapeutically relevant when antimitotic drugs are used." (PMID 39195284, 2024). "Our study confirmed a general trend for increased AURKA mRNA in cancer compared to normal tissues and revealed that AURKA expression is highly dependent on post-transcriptional control in several cancers." (PMID 39527514, 2024). "As summarized above, Aurora kinase A inhibition as a cancer therapeutic target is an ongoing area of research." (PMID 39199578, 2024). "Differences were observed with both positive and negative trends, indicating that using nonconforming datasets can lead to both overestimate and underestimate of changes in AURKA mRNA expression between cancer and normal samples." (PMID 39527514, 2024). "The literature mainly reports that AURKA overexpression in cancers is due to increased gene copy number, transcription, or protein stability." (PMID 39527514, 2024). "In this review, we examine 33 direct substrates of AURKA in various cancers, which have revealed the pleiotropic mechanisms by which they promote malignancy of different origins." (PMID 39334449, 2024). "Our review examines the most recent advances in AURKA regulation and its molecular mechanisms for promoting various cancers, with a particular focus on its disease-specific substrates and their associated signaling pathways." (PMID 39334449, 2024). "It was found that CDK1 overexpression in adrenocortical carcinoma cell (ACC) lines locked ACC cells at the G2/M checkpoint by interacting with UBE2C and AURKA/B, promoting cancer cell proliferation and inducing epithelial mesenchymal transition (EMT)." (PMID 39830349, 2024). "Studies have proposed that overexpression of AURKA leads to tumorigenic transformation and DNA instability, affecting response to cancer therapies." (PMID 39198859, 2024). "In light of this, the aberrant expression of AURKA/B in cancer emphasizes their potential value as therapeutic and drug-development targets." (PMID 38606093, 2024). "Investigations of the possible involvement of hsa-let-7a miRNA in AURKA expression in cancer were also performed." (PMID 39527514, 2024).
cancer (continued). "We then measured differences in the short/long ratio (SLR) of the two alternative cleavage and polyadenylation (APA) isoforms of AURKA mRNA across cancers compared to the respective healthy counterparts." (PMID 39527514, 2024). "Conversely, only 18% of cancer types exhibit AURKA expression with log2 (TPM + 1) values <2 such as brain lower‐grade glioma, prostate adenocarcinoma, and thyroid carcinoma." (PMID 38590119, 2024). "Emerging evidence highlights the critical role of non-coding RNAs (ncRNAs) in the regulation of Aurora kinase A (AURKA), one of the key hub genes involved in several key cancer pathways." (PMID 39598228, 2024). "AURKA-induced YAP1 phosphorylation was identified as a key trigger for cancer stem cell reprogramming." (PMID 38467828, 2024). "Most of these genes were cell cycle-related genes, including CHEK1, CDK1, RUVBL2, PSMD14, SUPT5H, RBX1, and AURKA, across 28 cancer types." (PMID 38972884, 2024). "Exploiting these cancer‐related pathways can offer a promising avenue for anti‐cancer therapies, especially with the identification of several AURKA inhibitors." (PMID 38590119, 2024). "We then probed the correlation of AURKA SLR to AURKA mRNA expression (‘mRNA vs SLR’) across the six cancers." (PMID 39527514, 2024). "LIMK2 inhibition or ablation can be considered as an alternative approach to modulating AURKA deregulation in cancer." (PMID 39334449, 2024). "Given the high mutation frequency of KEAP1 in NSCLC, our focus was primarily on this cancer type to identify specific indications for AURKA inhibitors." (PMID 38521813, 2024). "This utilised 13 cancer cell lines from four cancer types, treated with either an aurora-kinase A inhibitor, Alisertib, or the topoisomerase II inhibitor, etoposide." (PMID 39578455, 2024). "Most cancers showed an increase in mean AURKA SLR (AURKA-203) in cancer samples compared to respective matched normal samples (SLR fold change > 1)." (PMID 39527514, 2024). "Accordingly, anti-cancer strategies aimed at reducing AURKA expression levels have been shown to be effective in suppressing the carcinogenicity of AURKA." (PMID 39527514, 2024). "We investigated to what extent post-transcriptional regulation is responsible for defining and dysregulating AURKA expression in human cancers." (PMID 39527514, 2024). "Aurora kinase A (AURKA) is crucial in regulating cell division and maintaining genomic stability, making it significant in cancer biology." (PMID 41907711, 2024). "The relationship between AURKA protein expression and hsa-let-7a expression (‘protein vs hsa-let-7a’) was then explored for the 18 cancers of interest." (PMID 39527514, 2024). "THCA represents the only example in which AURKA mRNA is lower in cancer compared to normal tissue, although its expression is overall very low, and this difference is therefore non-significant." (PMID 39527514, 2024). "This review specifically focuses on 33 of such direct cancer-specific targets of AURKA and the signaling cascades by which it promotes oncogenic phenotypes." (PMID 39334449, 2024). "In contrast, in cancer tissues, AURKA is overexpressed in a cell-cycle-independent manner and is mislocalized in the cytoplasm and/or nucleus depending upon the cancer." (PMID 39334449, 2024). "As observed in studies with cancer cells, AURKA protein interacts more strongly with CCT137690 than AURKB, which is also the case for the tick proteins." (PMID 39542861, 2024). "Targeting AURKA and other tumor suppressors results in cancer cell death, highlighting a promising target for cancer treatment." (PMID 39433125, 2024). "To validate the sensitizing effect of KEAP1 mutation or deficiency on AURKA inhibitors, we initially analyzed the sensitivity of NSCLC cell lines with wildtype or mutant KEAP1 to AURKA inhibitors in the Cancer Drug Sensitivity Genomics database GDSC." (PMID 38521813, 2024). "It has become gradually evident that AURKA's functions extend beyond regulating the cell cycle in cancer." (PMID 38590119, 2024).
cancer (continued). "Under hypoxic conditions, AURKA can promote cancer cell survival and proliferation via the AKT and p38/mitogen-activated protein kinase (MAPK) cascades." (PMID 39598228, 2024). "In cancer, where AURKA is overexpressed, it leads to mitochondrial fusion, thus producing more energy to fuel rapidly proliferating cells." (PMID 39334449, 2024). "AURKA is an established target for cancer therapy; however, the efficacy of its inhibitors in clinical trials is hindered by differential response rates across different tumor subtypes." (PMID 38521813, 2024). "The centrosomal localisation of AurkA, the identification of its centrosomal targets, and the frequent occurrence of centrosome abnormalities in cancer cells suggest this as a potential route to chromosomal instability following AurkA overexpression." (PMID 39195284, 2024). "AURKA has been observed to be overexpressed in multiple cancers and is involved in centrosome segregation, mitotic time conditions and spindle assembly." (PMID 39063036, 2024). "PLK1 and AURKA are commonly overexpressed and are recognized as promising therapeutic targets in a wide range of cancers, including for SCLC." (PMID 39085197, 2024). "First, a positive correlation (r > 0.1) between AURKA SLR and protein expression levels (‘protein vs SLR’) was found in six cancers, suggesting that APA modulates AURKA expression in these cancers (UCEC, BRCA, KIRP, LUAD, READ, KIRC)." (PMID 39527514, 2024). "AURKA overexpression in HCC has been shown to profoundly influence various critical features of cancer cells, including proliferation, survival, migration, and invasion, indicating its significant involvement in disease development and progression." (PMID 38590119, 2024). "Over the years, extensive research has revealed the multifaceted roles of AURKA in cancer development and progression." (PMID 38590119, 2024). "Over the years, various studies identified several compounds able to inhibit AURKA in vitro, with some accumulating sufficient evidence to undergo further evaluation as potential cancer therapies during preclinical or clinical trials." (PMID 38590119, 2024). "In order to explore the contribution of post-transcriptional regulation to AURKA expression in different cancers, we carried out a meta-analysis of -omics data of 18 cancer types from The Cancer Genome Atlas (TCGA)." (PMID 39527514, 2024). "The activation of AURKA and AURKB has been shown to play an important role in multiple cancers, and their overexpression is generally associated with tumor cell invasion and metastasis." (PMID 39045407, 2024). "The D132A mutation of AURKA blocks the activation of cleaved caspase 3 and EGR1 expression, reducing the sensitivity of cancer cells to the chemotherapeutic drug Taxol in vitro and in vivo." (PMID 38994036, 2024). "Next, how AURKA mRNA expression correlated with protein expression (‘protein vs mRNA’) was examined in cancer samples." (PMID 39527514, 2024). "Our results suggest that mechanisms affecting AURKA translation or protein degradation are involved in tuning AURKA protein expression in various cancers, with a role of increasing importance as the degree of mRNA-protein correlation decreases." (PMID 39527514, 2024). "As a consequence, impairments in mechanisms affecting mRNA dynamics offer a substantial basis for alterations in AURKA protein expression in cancer." (PMID 39527514, 2024). "In conclusion, the data presented here cumulatively suggest that post-transcriptional mechanisms can constitute the primary form of regulation of the expression of AURKA in some cancers." (PMID 39527514, 2024). "In this article, analysis of protein and mRNA expression of AURKA in all cancers was performed using genomic datasets available from TCGA and explored in previous published studies." (PMID 39527514, 2024). "Overexpression of AURKA and AURKB has been observed in various cancers, including NSCLC, and is associated with poor prognosis and drug resistance." (PMID 38600056, 2024).